EGFR (epidermal growth factor receptor)
Diseases named in the same sentence as EGFR in open-access papers (continued):
Sharing a sentence is not in itself a finding about the gene and the disease.
cancer (continued). "The integration of liquid biopsy, utilizing techniques such as the Oncomine Pan-Cancer Cell-Free Assay and Cobas® EGFR Mutation Test, provided valuable insights into the genetic landscape of these patients." (PMID 40027142, 2024). "EGFR mutations, commonly, either exon 21 L858R insertion or deletion on exon 19, trigger uncontrolled activation of the EGFR receptor, promoting cancer cell growth and survival." (PMID 38540317, 2024). "Hyperactivation of EGFR in cancer has been attributed to activating mutations, gene amplification, aberrant gene expression, and defective endocytosis/degradation." (PMID 38260423, 2024). "Both EGFR mutations and EGF/EGFR hypo‐methylation activated the EGFR pathway, fueling cancer growth." (PMID 39036344, 2024). "ACSL4 upregulated by bone morphogenetic protein 4 (BMP4) enhances the cancer cell fatty acid metabolism, which is associated with acquired drug resistance in EGFR-mutant NSCLC cells." (PMID 38539505, 2024). "Nevertheless, the practical utility of EGFR is constrained by the presence of EGFR mutations, cancer heterogeneity, and the inevitable development of drug resistance." (PMID 38389844, 2024). "In several experimental settings, LDH-A inhibition appeared to cause inhibition of EGFR-mediated signaling and, recently, it was also shown to abrogate cancer cell resistance to EGFR tyrosine kinase inhibitors." (PMID 39329717, 2024). "Mutations or genetic variations in EGFR alone cannot account for all the differences in cancer patients’ responses to EGFR-targeted treatments." (PMID 39273318, 2024). "The overexpression of EGFR and closely related ErbB2 have been associated with more aggressive cancer symptoms." (PMID 39496648, 2024). "Epidermal growth factor receptor (EGFR) is a heavily glycosylated transmembrane receptor tyrosine kinase that is closely associated with tumorigenesis and cancer proliferation." (PMID 39138197, 2024). "The mechanism of action of furmonertinib was characterized through ATPase assays, revealing its interaction with ABCB1 and ABCG2,suggesting a potential strategy to overcome resistance in EGFR exon 20ins-mutated cancers." (PMID 39743996, 2024). "In this way, it is possible to quantify (copies/mL) and identify, if present, variants relating to the mutated EGFR, perhaps due to targetable resistance mechanisms involved in resistance to cancer therapy." (PMID 38893088, 2024). "Here, we applied our AutoPepVax program to select neoantigens derived from common EGFR missense mutations across four cancers." (PMID 38675381, 2024). "With this, many have made use of EGFR inhibitors, as most of the EGFR mutations in cancer cells cause overactivation of the PI3K-Akt pathway." (PMID 38666818, 2024). "AutoPepVax was used to determine the positive EHLA-I and EHLA-II pairs for prevalent EGFR mutations across various cancers." (PMID 38675381, 2024). "Gefitinib is an EGFR tyrosine kinase inhibitor used to treat patients with cancer exhibiting EGFR mutations." (PMID 38745775, 2024). "This method enabled to distinguish cancer causing mutations from wild-type EGFR alleles and precisely eliminate cancer causing mutant EGFR alleles." (PMID 38666293, 2024). "Clinical trials exploring treatments for EGFR- or KRAS-mutated (EGFRmut or KRASmut) cancers have focused on small-molecule inhibitors targeting the driver mutations." (PMID 38639476, 2024). "EGFR-TKI treatment was administered to 44 ASC patients with EGFR mutations at the two cancer centers for the purposes of assessing efficacy." (PMID 39026979, 2024). "Previous studies have demonstrated that, during treatment with EGFR inhibitors, cancer cells can acquire somatic mutations in the EGFR gene, significantly reducing the drugs’ affinity for EGFR." (PMID 39897079, 2024). "In summary, combining EGFR-tyrosine kinase inhibitors with α-PD-1/PD-L1 therapy has the potential to maximize the effectiveness of immunotherapy in individuals diagnosed with EGFR-mutated cancers." (PMID 38462628, 2024).
cancer (continued). "The prolonged exposure of EGFR-driven cancer cell lines to NETs caused the activation of the EMT program through the upregulation and cleavage of Notch 1 and was confirmed by the enhanced expression of EMT markers." (PMID 39430758, 2024). "Mechanistically, it is shown that YY1 signaling upregulates IL32 secretion in PCs, subsequently activating the β5‐integrin‐Src‐Akt pathway in EGFR‐mutated cancer cells, contributing to their TKI sensitivity." (PMID 39435643, 2024). "EGFR-inhibitor-acquired resistance is associated with the development of RAS mutant clonal cancer cell populations that regress upon EGFR inhibitor cessation, providing rationale for potential benefit from EGFR inhibitor rechallenge." (PMID 38672633, 2024). "We next focused on the adenocarcinomas and looked into the common cancer gene mutations in EGFR and KRAS." (PMID 38473297, 2024). "They act as irreversible EGFR inhibitors, effectively managing cancer progression induced by EGFR-TKI-sensitive and T790M-resistant mutations, with an added advantage of controlling brain metastases." (PMID 39211774, 2024). "The interaction between EGF and EGFR is a key molecular mechanism that contributes to cell growth and survival, and dysregulation of this pathway is often associated with cancer development and progression." (PMID 38343537, 2024). "The PI3K-AKT pathway, strongly associated with cancer growth and prognosis, represents one of the signaling cascades that undergo hyperactivation upon EGFR activation." (PMID 38613804, 2024). "Numerous studies have indicated that alterations in the ErbB receptor are linked to various cancers, with EGFR directly regulating phosphatidylinositol 3‐kinase/protein kinase B (PI3K/Akt)." (PMID 39479720, 2024). "Cancer cells can adapt through a variety of mechanisms, including secondary mutations in the EGFR gene and alternative signaling pathways." (PMID 39652601, 2024). "EGFR p.E709_T710delinsD (c.2127_2129delAAC) in exon 18 is registered in the Catalogue of Somatic Mutations In Cancer (COSMIC; ID: COSV51779132) and the corresponding drug is afatinib with level 3A bases on OncoKB." (PMID 38238401, 2024). "Dysregulation of EGFR signaling has been implicated in multiple cancer types, making it an attractive target for cancer therapy." (PMID 39130636, 2024). "EGFR is frequently mutated and/or overexpressed in different types of human cancers and the molecular target of multiple cancer therapies." (PMID 38745188, 2024). "Activation of STAT3 by JAK leads to transcriptional induction of the JAK inhibitor SOCS3 by STAT323, suggesting that STAT3 activity can oscillate in JAK-activated cancer cells and EGFR-mutated cancer cells." (PMID 38760429, 2024). "EGFR overexpression is linked to the pathogenesis of cancer, by enhancing cell growth and proliferation, and is estimated to be found in 27.4% of iCCA patients and 19.2% of eCCA patients." (PMID 38339363, 2024). "Collectively, our data are in agreement with previous studies suggesting that the loss of EGFR expression is a mechanism involved in the resistance to gefitinib of cancer cells exposed to optimal doses of gefitinib." (PMID 38732063, 2024). "Overexpression, gene amplification, or mutations in EGFR are correlated with poor prognosis and clinical outcome in many types of cancer, such as lung, breast, brain, head and neck, ovarian, cervical, bladder, and esophageal cancer." (PMID 39339249, 2024). "For instance, EGFR (Epidermal Growth Factor Receptor) is a gene that encodes the epidermal growth factor receptor, which is widely recognized for its significance in cancer." (PMID 39581873, 2024). "Inhibition of GDP-fucose synthesis leads to decreased fucosylation of receptors implicated in the EGFR signaling pathway and, thus, reduces cancer cell proliferation." (PMID 39123480, 2024).
cancer (continued). "Our study established a clear link between the EGFR C797S mutation and elevated PDK1 expression, opening new avenues for the discovery of targeted therapies and improving our understanding of the roles of EGFR mutations in cancer progression." (PMID 38689087, 2024). "Although EGF has been mostly associated with cancer, in studies mostly focused on EGFR activation, this molecule has other potential functions." (PMID 39110087, 2024). "Prognostically, EGFR mutations are associated with poor survival and cancer progression, while EGFR high expression has been identified as a negative predictor of overall survival (OS) in CCA." (PMID 39199659, 2024). "Resistance to epidermal growth factor receptor (EGFR) tyrosine kinase inhibitors (TKIs) has been considered the primary cause of treatment failure and cancer recurrence in patients with EGFR-mutant non-small cell lung cancer (NSCLC)." (PMID 39143065, 2024). "The PDO media utilized in this study contain human EGF, and it is therefore possible that excessive EGFR signaling due to the combination of a Kras mutation and additional EGFR activation by EGF in the media leads to cancer cell apoptosis." (PMID 38542253, 2024). "Increased Egfr transcript levels and EGFR protein levels are associated with poor prognosis in various cancers." (PMID 38935814, 2024). "COX-2 and EGFR are frequently overexpressed in several malignant tumors associated with various diseases." (PMID 38248333, 2024). "Epidermal growth factor receptor (EGFR), a member of the ErbB receptor tyrosine kinase family, is implicated in various malignant tumors." (PMID 39451714, 2024). "Excessive expression of the EGFR leads to aberrant signal transduction and is directly associated with the development of cancer." (PMID 39404419, 2024). "Abnormal expression levels of AREG in cancer cells have been associated with resistance to anti-EGFR therapy in patients." (PMID 39452130, 2024). "To confirm that IL‐32 is the downstream effector of YY1‐mediated PC effects on EGFR‐mutated cancer cell sensitivity to TKI, we exposed these cells to CM from YY1‐depleted PCs in the presence of TKI drugs, with or without IL32 treatment." (PMID 39435643, 2024). "Modified exosomes with multivalent antibodies on the surface specific to T-cell CD3 and cancer-cell-associated EGFR redirect and activate cytotoxic T cells toward cancer cells for killing." (PMID 38667297, 2024). "The study proposed an imbalance in the inhibitory relationship between USP43 and EGFR/PI3K/AKT as a potential cause of cancer growth." (PMID 38613804, 2024). "In the case of EGFR mutations, clinically commonly treated with tyrosine kinase inhibitors are more likely to develop acquired resistance, which leads to metastasis of cancer." (PMID 39247621, 2024). "We discovered that EGFR is the protein most negatively associated with ZNRF3/RNF43 expression using proteogenomic data of cancer patients, and that ZNRF3/RNF43 interact with EGFR and down-regulate EGFR through ubiquitination and degradation." (PMID 38260423, 2024). "In the context of cancer prognosis, EGFR overexpression is associated with shorter recurrence times, increased recurrence rates, and reduced survival durations." (PMID 38699644, 2024). "Our research probes the mechanistic role of HSP90B1 in regulating the PI3K/Akt/mTOR pathway, a key downstream effector of EGFR signaling implicated in the oncogenesis of various cancers." (PMID 38711062, 2024). "Several EGFR extracellular domain variants are dacomitinib-sensitive in vitro and we observed clinical response to dacomitinib in patients whose cancers harbor the G598V mutation." (PMID 38548752, 2024).
cancer (continued). "EGFR mutations leading to its overexpression or amplification are associated with a number of cancers and are often observed in GBM." (PMID 38674026, 2024). "EGFR and Wnt/β-catenin signaling are two of the pathways implicated in the oncogenesis and cancer progression induced by both THBS1 and THBS2, as well as in the activation of the EMT program." (PMID 38339060, 2024). "EGFR tyrosine kinase inhibitors (EGFR TKIs) and monoclonal antibodies (mAbs) are used in the treatment of cancers with activated EGFR mutations." (PMID 39065626, 2024). "Another target in our top modules was EGFR, whose overexpression and mutations are well explored in the cancer domain, with the primary function including the initiation of tyrosine kinase signaling cascades." (PMID 38651367, 2024). "EGFRi treatment is prescribed for cancer patients who harbor specific EGFR mutations that confer EGFR dependency, ensuring the efficacy of the treatment." (PMID 38551001, 2024). "Recently, cancer therapy has entered an era of precision medicine, which benefits from discovering oncogenic driver gene alterations, among which epidermal growth factor receptor (EGFR) mutation is the most frequent targetable mutation type in LUAD." (PMID 38472205, 2024). "An illustration of this is seen in the study focusing on EGFR mutations, which specifically involves patients already presenting with bone metastases, potentially failing to accurately represent the broader cancer population." (PMID 38791037, 2024). "EGFR signaling in cancers has been associated with global metabolism favoring highly glycolytic tumors." (PMID 38916448, 2024). "Autophagy is widely known to be strongly linked to drug resistance and cancer progression, and the study has also demonstrated that the EGFR-mediated RAS/RAF/MEK/ERK pathway regulates autophagy and is a critical factor in a variety of malignancies." (PMID 39574469, 2024). "This is important in the context of cancer susceptibility, side effects, and response rate to EGFR and VEGF-targeting drugs." (PMID 39403135, 2024). "This targeted inhibition is of significance due to the diminished responsiveness of cancer cells with these mutations to earlier generations of EGFR inhibitors." (PMID 38611728, 2024). "IL32 then activates the β5‐integrin‐Src‐Akt pathway, which impairs TKI effectiveness in EGFR‐mutated cancer cells." (PMID 39435643, 2024). "We applied AutoPepVax to the design of a pan-cancer peptide vaccine targeting EGFR missense mutations." (PMID 38675381, 2024). "Significantly, Cilengitide treatment inhibited the augmented colony formation and invasive potential seen in EGFR‐mutated cancer cells treated with placebo, which were exposed to CM from PCs along with TKI drugs." (PMID 39435643, 2024). "GBM was the first cancer type that was comprehensively analysed by genomics methods, and careful analysis revealed that the epidermal growth factor receptor (EGFR) gene is amplified or mutated in 40–60% of GBM cases." (PMID 38638676, 2024). "Dysregulation of EGFR signaling results in gene amplification and overexpression, and activating mutations of EGFR have been identified in a variety of cancers." (PMID 39357822, 2024). "From a vertical signaling cascade standpoint, the three commonly mutated effectors of the ERKp in human cancer are arranged as EGFR, KRAS, and BRAF." (PMID 38485987, 2024). "In cancer medicine, there is a growing focus on pharmacologically disrupting USP activity to specifically target cancer-causing protein abnormalities, including EGFR." (PMID 39695128, 2024). "Nrp2 expression is inversely associated with EGFR expression in cancer cells and inhibits the rescue pathways within EGFR- or MET-addicted carcinoma cells, likely through NF-κβ repression." (PMID 38592275, 2024). "Targeted therapies are also now FDA-approved in the adjuvant setting for EGFR-mutated cancers and ALK-mutated cancers per the ADAURA, LAURA, and ALINA trials." (PMID 39518093, 2024).
cancer (continued). "An endogenous exosome carrying CD3 and a monoclonal antibody specific to cancer cell-associated EGFR has been designed and generated." (PMID 38835784, 2024). "NSCLC is the predominant cause of cancer-related mortality globally, with approximately 17% of patients presenting with activating mutations in the EGFR gene." (PMID 38892307, 2024). "In conclusion, our study reveals the previously unrecognized role of pericytes in modulating the sensitivity of EGFR‐mutated cancer cells to TKI treatment." (PMID 39435643, 2024). "The combination of statins with EGFR-TKIs therapy has been associated with prolonged OS in patients with lung cancer, indicating a synergistic anti-cancer effect." (PMID 39308527, 2024). "EGFR mutations leads to constitutive activation of the gene and results in cancer phenotypes, with EGFR overexpression observed in DIPG." (PMID 38774284, 2024). "It and its main metabolite effectively target cancers with sensitive EGFR mutations and the T790M resistance mutation, while minimally affecting wild-type cells." (PMID 39743996, 2024). "EGFR mutations affecting the expression of this gene can lead to uncontrolled cell growth and cancer." (PMID 38674026, 2024). "Various mutations in EGFR, a tyrosine kinase receptor gene, are prominent drivers in the development and progression of several cancers, including GBM." (PMID 39062807, 2024). "Collectively, these findings strongly suggest that the combination of osimertinib and leelamine is a promising therapeutic approach for EGFR-mutant cancers, particularly those with the challenging C797S mutation, which confers resistance to osimertinib." (PMID 38689087, 2024). "The cancer-related gene alterations reported in the two cohorts were similar (86.2% vs. 86.6%), with EGFR having the highest mutation frequency in both." (PMID 38902688, 2024). "The increased expression of epidermal growth factor receptor (EGFR) has been associated with the development of various human cancers, including non-small cell lung cancer (NSCLC)." (PMID 39130636, 2024). "The abnormal activation of the TGF-α/EGFR autocrine loop, observed in many malignant tumors, underscores its close association with tumorigenesis and progression." (PMID 38594466, 2024). "Preclinical studies of dacomitinib showed potent activity against cancer cells harboring EGFR mutations and provided insight into its pharmacodynamics, indicating a longer duration of receptor downregulation compared to the first-generation TKIs." (PMID 38611728, 2024). "While EGFR inhibition provides survival benefit in carcinomas expressing EGFR variants in residues of the kinase domain, these inhibitors have not been successful in GBM." (PMID 38892466, 2024). "The analysis revealed significant associations between EGFR mutation positivity and age group (<50 years: lower risk) and carcinoma type (adenocarcinoma: increased risk)." (PMID 39429333, 2024). "Knock down of EndoB in LNCaP cells, a human epithelial carcinoma cell line, results in increased epidermal growth factor receptor signaling due to deficient receptor endocytosis." (PMID 38474321, 2024). "Adenocarcinoma showed a strong association, increasing the risk of EGFR positivity compared to other carcinoma types." (PMID 39429333, 2024). "EGFR overexpression has been reported in many types of cancer and has been associated with aggressive behavior and poor prognosis." (PMID 37114127, 2023). "Abnormalities cause most cancers in the epidermal growth factor receptor (EGFR)/phosphatidylinositol 3-kinase (PI3K)/mammalian target of rapamycin pathway, hypoxia-inducible factor (HIF), and vascular endothelial growth factor (VEGF) expression." (PMID 37037467, 2023).